LPL (lipoprotein lipase)
Diseases named in the same sentence as LPL in open-access papers (continued):
Sharing a sentence is not in itself a finding about the gene and the disease.
coronary artery disease (continued). "This LPL mutation S447X is the only mutation that has a protective effect against the development of HTG and coronary heart disease by decreasing plasma TG levels in the clinic and increasing HDL production." (PMID 24646025, 2014). "Due to their influence on lipid metabolism and coagulation processes, LPL, PROCR (endothelial cell protein C receptor) and PDGF may affect the atherosclerotic process and, thus, the risk of coronary heart disease." (PMID 38392646, 2024). "Similarly, a high HDL-ApoE concentration has also been linked to a higher risk of coronary heart disease events due, in part, to the increased production of VLDL (very-low-density lipoprotein) and lower VLDL lipolysis by lipoprotein lipase." (PMID 38732018, 2024). "Representative examples of such genes include those encoding lipoprotein lipase (LPL), where variants increase risk of coronary artery disease via perturbation of triglyceride metabolism, and checkpoint kinase 2 (CHEK2), which increases risk of breast cancer via perturbation of DNA repair pathways." (PMID 32820175, 2020). "For a given genetic difference in LDL-C, the association with lower risk of coronary disease conveyed by rare loss-of-function variants in ANGPTL3, which are associated with lower LDL-C levels and enhanced LPL lipolysis, was greater than that conveyed by other LDL-C–lowering genetic mechanisms." (PMID 30326043, 2018). "By analyzing individual-level genetic data in close to 400 000 people, we provide strong evidence that triglyceride-lowering alleles in the LPL pathway and LDL-C–lowering genetic mechanisms are independently associated with a lower risk of coronary artery disease." (PMID 30326043, 2018). "Additionally, pre-heparin serum LPL has been shown to be inversely related to the progression of coronary artery disease in young/middle–older aged populations (Hitsumoto, Ohsawa: 22–79 years, Rip, Nierman: 45–79 years), highlighting that pre-heparin serum LPL is anti-atherogenic." (PMID 31644560, 2019). "Interestingly, recent cohort studies suggest that LPL 447X carriers appear to have a more favorable lipid profile and this allele appears to be a negative risk factor for coronary artery disease (CAD)." (PMID 16822320, 2006). "The increased activity of LPL by decreasing TG and raising the HDL‐C levels can provide protection against T2DM and its complications, such as coronary artery diseases." (PMID 36605456, 2023). "Moreover, the LPL gene encoding lipoprotein lipase, an enzyme responsible for hydrolyzing triglyceride particles and indirectly responsible for the production of HDL-C, was investigated in relation to coronary heart disease, and the diversified influence of different mutations has been established." (PMID 35893405, 2022). "Lipoprotein lipase (LPL) is widely linked to lipid and lipoprotein metabolism, but its effects on coronary artery disease (CAD) are not clearly elucidated." (PMID 29459423, 2018). "Lipoprotein lipase (LPL) is a key enzyme in lipoprotein metabolism and a major candidate gene for coronary heart disease." (PMID 26445370, 2015). "For example, loss-of-function mutations in apolipoprotein C3 (APOC3), which is an inhibitor of LPL, decrease the risk of coronary artery disease (CAD), while loss-of-function mutations in apolipoprotein A5 (APOA5), which is an activator of LPL, increases the risk of CAD." (PMID 27039080, 2016). "Of these SNPs, rs964184(APOA5-A4-C3-A1) was also related with the presence of coronary artery disease in a large GWAS for coronary artery disease, although very recently also rs2954029(TRIB1) and rs264(LPL) were identified in a GWAS for coronary artery disease." (PMID 24979386, 2014).
coronary artery disease (continued). "The influence of the triacylglycerol lipases on multivessel coronary artery disease has not been fully elucidated, most likely because LPL and EL may exert both anti-atherosclerotic and pro-atherosclerotic effects." (PMID 37686357, 2023). "Additionally, neither the mRNA nor the protein levels of CS, FAT/CD36, or LPL as well as FAS, SREBP-1c and GPAT1 changed significantly in subjects with multivessel coronary artery disease." (PMID 31979197, 2020).
Hepatic steatosis (53 papers, 2011 to 2026). Steatosis is a term used to denote lipid accumulation within hepatocytes. "Insulin and ANGPTL4 are key, opposing regulators of LPL activity, insulin enhances LPL, whereas ANGPTL4 inhibits it, and LPL activity is closely linked to circulating free fatty acid levels and the development of hepatic steatosis." (PMID 41226996, 2025). "In obesity, the impaired ability to up-regulate LPL by insulin exacerbates hepatic postprandial lipid load, thus causes hepatic steatosis." (PMID 23554788, 2013). "This study aims to explore serum levels of FAS protein and LPL activity in patients with steatosis in order to assess a possible clinical association between levels of enzyme expression and degree of liver steatosis." (PMID 23110339, 2012). "Furthermore, stimulation of lipoprotein lipase activity has been shown to be associated with reduced serum triglyceride concentrations in subjects with hepatic steatosis." (PMID 33327560, 2020). "This study aims to investigate if circulating levels of FAS and LPL could be clinically associated with liver steatosis." (PMID 23110339, 2012). "Research indicates that patients with severe liver steatosis exhibit significantly higher serum LPL activity compared to those with mild or moderate steatosis." (PMID 40868056, 2025). "And then the activation of lipoprotein lipase has been shown to be effective in reducing the severity of hepatic steatosis." (PMID 38325840, 2024). "Inhibition of LPL activity promotes hepatic uptake of triglycerides from chylomicron remnants, leading to the development of hepatic steatosis." (PMID 36798663, 2023). "We found that feeding had a significant positive effect on ribosome occupancy of 49 mRNAs associated with hepatic steatosis (e.g., LIPE, LPL), but this effect was blunted in the liver of rats fed a WD." (PMID 36387860, 2022). "An FF-induced increase in Lpl expression in HHTg rats suggests that the beneficial effects of FF on circulating lipids and hepatic steatosis can be mediated by PPARα-activated LPL." (PMID 35678658, 2022). "The over-expression of FAS was also associated with the degree of liver injury, suggesting that two enzymes, FAS and LPL, can be considered valid biomarkers of liver steatosis." (PMID 33918878, 2021). "As LPL activity is necessary for the clearance of triglycerides from VLDL in peripheral tissues, decreased LPL activity slows triglyceride transport from the liver to peripheral tissues and promotes the development of liver steatosis." (PMID 31815184, 2019). "The subjects with severe steatosis had significantly higher serum levels of FAS protein and LPL activity compared to subjects with mild and moderate liver steatosis." (PMID 23110339, 2012). "Our results demonstrate that furin-resistant LPL lowers longitudinal plasma triglyceride levels without causing adverse effects such as hepatic steatosis." (PMID 42165204, 2026). "The activation of LPL has been confirmed to reduce the severity of hepatic steatosis effectively." (PMID 39752447, 2025). "The effect of FOXA2 on LPL is clear, but further studies are needed to determine whether it can influence fatty acid uptake and liver steatosis through this pathway." (PMID 36798663, 2023). "During the development of fatty liver-associated comorbidities such as T2D and obesity, the liver secretes large amounts of VLDL particles that eventually lead to elevated levels of plasma FA uptake through lipase activity (LPL)." (PMID 36477411, 2022). "Thus, we performed histological analysis to determine hepatic steatosis in the livers of 12 months WT and LPL KD mice." (PMID 32998280, 2020). "As this inhibition of triglyceride transport is rescued in leptin-deficient mice, regulating VLDL metabolism by hepatic VLDLR, LPL, and leptin may represent a new therapeutic strategy for preventing diet-induced liver steatosis." (PMID 31815184, 2019).
Hepatic steatosis (continued). "PPARγ, activated as PPARγ-retinoid x receptor functional heterodimer, contributes to FFAs uptake and hepatic steatosis through PPARγ-responsive genes, such as lipoprotein lipase (LPL), fatty acid translocase, fatty acid transport proteins and adipocyte protein 2 (aP2)." (PMID 28081181, 2017). "Thirdly, upregulated LPL expression may contribute to hepatic steatosis by increasing intracellular free fatty acid accumulation through hydrolysis of lipoprotein triglyceride." (PMID 24146946, 2013). "Moreover, stratifying for score of steatosis, the subjects with severe steatosis had significantly higher serum levels of FAS protein and LPL activity compared to subjects with mild and moderate liver steatosis." (PMID 23110339, 2012). "Increased serum levels of FAS expression and LPL activity could be considered a marker of severe liver steatosis." (PMID 23110339, 2012). "FAS and LPL, intracellular proteins, appear to exit cells during liver impairment and their presence in serum could be considered a marker of liver steatosis." (PMID 23110339, 2012). "Although LPL expression in the pancreas is relatively low, evidence indicates that elevated VLDL levels contribute to the development of pancreatitis, as a common condition among obese and T2D patients, and are further known to be associated with fatty liver disease." (PMID 36477411, 2022). "Interestingly, loss of hepatic lipases function resulted in an increased liver steatosis in mice and LPL being expressed in non-parenchymal cells in the liver, is certainly involved in hepatic fibrogenesis." (PMID 33918878, 2021). "SREBP also increases the liver steatosis; its activation induces the expression of FAS and LPL, which regulate the fatty acid metabolism." (PMID 37007480, 2023). "In normal individuals, LPL activity in the adipose tissue is essential in buffering the circulatory TAG load, which protects against ectopic TAG accumulation, including hepatic steatosis." (PMID 23554788, 2013). "In this study we describe a relationship between human liver steatosis and elevated levels of circulating lipogenic enzymes expression, such as FAS and LPL." (PMID 23110339, 2012). "One study reported lower ANGPTL4 concentrations in adults with hepatic steatosis compared with healthy controls, positing that reduced ANGPTL4 leads to disinhibition of LPL, enhanced hydrolysis of circulating triglycerides, and increased free fatty acid flux to the liver." (PMID 41226996, 2025). "In conclusion, the reduced levels of LPL, FASN, and SCD1 in liver and adipose tissue of IKKε knockout mice are in accordance with the observed lower lipid accumulation in serum and reduction of liver steatosis." (PMID 39409049, 2024). "Maintained LPL activity promotes the clearance of triglycerides from VLDL in peripheral tissues, which can accelerate triglyceride transport from the liver to peripheral tissues and contribute to the improvement of liver steatosis." (PMID 31815184, 2019). "Moreover, morbidly obese individuals show statistically increased hepatic LPL activity compared to controls, independent of liver fibrosis or fatty liver presence." (PMID 40868056, 2025). "In addition, we also found an ≍6-fold and ≍2-fold increase in expression of LpL and SREBP1c mRNA, respectively, in the livers of the ApoC3Tg mice following HFD, which may also have contributed to the development of hepatic steatosis in these mice." (PMID 21793029, 2011). "In contrast to what has been reported in human and mouse studies, the highly significant upregulation of PPARG, CD36, LPL, and FABP4 in the liver of the minipigs do not result in development of abundant hepatic steatosis." (PMID 32205840, 2020). "Our results show that Göttingen Minipigs do not develop abundant hepatic steatosis in spite of the significantly increased expression of PPARG, FABP4, CD36, and LPL in the liver." (PMID 32205840, 2020).
Hypercholesterolemia (49 papers, 2008 to 2025). An increased concentration of cholesterol in the blood. "Many GWASs have reported the association between SNPs in the LPL gene (rs12678919, rs328, rs10503669, rs17411031, rs10096633, rs17482753, rs2083637) and hypercholesterolemia, especially related to HDL-C level." (PMID 37510094, 2023). "Inactivated lipoprotein lipase enzyme due to insulin deficiency during diabetic condition caused secondary complications from hypertryglyceridemia and hypercholesterolemia." (PMID 35620596, 2022). "These genetic disorders include LPL -/-, apoE 2/2, apoE 4/4, homozygous familial hypercholesterolemia, homozygous familial defective apoB, and S447X - a single nucleotide polymorphism in the LPL gene." (PMID 22029862, 2011). "Polymorphisms of the LPL gene (D9N and N291S) have been shown to cause an increase in TC and TG and a decrease in HDL-C level, determining a phenotype specific to hypercholesterolemia." (PMID 37510094, 2023). "Several studies have reported that the mutations in LPL gene such as D9N and N291S cause an increase in total cholesterol and TG levels and a decrease in HDL-C level producing a hypercholesterolemia phenotype." (PMID 28577571, 2017). "We found that mutations in lipase A (LIPA) and lipoprotein lipase (LPL) cause symptoms such as nodular changes affecting the eyelids, hypercholesterolemia, hepatosplenomegaly and xanthomatosis." (PMID 26055101, 2015). "Increased HDL catabolism, free fatty acid flux, and impaired lipoprotein lipase results in higher TG levels, hypercholesterolaemia and lower HDL levels." (PMID 25395912, 2014). "For example, evinacumab, an antibody that inhibits ANGPTL3 not only reduces TG level in circulation by enhancing LPL activity but also significantly decreases low-density lipoprotein cholesterol (LDL-C) in patients with familial hypercholesterolemia (FH) in two independent phase 3 trials." (PMID 35187136, 2022). "In addition, LPL-mediated TG hydrolysis to produce fatty acids can significantly reduce the expression of the cholesterol transporter in macrophages and then reduce both cholesterol outflow and hypercholesterolemia." (PMID 34681767, 2021). "New therapies targeting the LPL inhibitors, ApoC‐III and ANGPTL3, have recently been trialled in adults with FCS and homozygous familial hypercholesterolemia, respectively." (PMID 38974610, 2024). "Although HDL levels are regulated by cholesteryl ester transfer protein, hepatic TG lipase and lipoprotein lipase etc., the increased HDL and LDL levels may be an event secondary to hypercholesterolemia induced by feeding HFCBD in mice." (PMID 22989092, 2012). "The results from our study showed that LPL-mediated VLDL lipolysis was disturbed in young and middle-aged subjects asymptomatic for CVD but with lipid disturbances—not only in those with elevated TG and LDL-C concentration but also in those with isolated hypercholesterolemia." (PMID 33917704, 2021).
type I hyperlipoproteinemia (45 papers, 2008 to 2025). "Of the 12 homozygous variants identified, 11 can be assigned as causative for typical FCS or LPL deficiency based upon disease phenotype, age of disease onset and/or in vivo LPL activity." (PMID 37568214, 2023). "Lipoprotein lipase deficiency (LPLD) (a monogenic autosomal recessive disease) is caused by homozygous or compound heterozygous mutations in the LPL gene." (PMID 37510094, 2023). "Mutations leading to LPL deficiency have been extensively characterized to better understand the causes of familial hyperchylomicronemia." (PMID 37142573, 2023). "Lipoprotein lipase deficiency (LPL) is a rare autosomal recessive disorder characterized by impaired TG metabolism due to a mutation in the LPL gene." (PMID 37630727, 2023). "It was approved by EMA in 2012 for the treatment of lipoprotein lipase deficiency, a metabolic genetic disorder in which a person has a defective gene for lipoprotein lipase." (PMID 35079633, 2022). "Different types of homozygous or heterozygous compound mutations in the LPL gene cause Lipoprotein lipase deficiency (LPLD deficiency), a rare autosomal recessive monogenic disorder." (PMID 35743896, 2022). "In 2012, the European Medicines Agency (EMA) approved the first-ever AAV-based gene therapy Glybera, a recombinant AAV product that delivers the human lipoprotein lipase (LPL) gene to treat hereditary lipoprotein lipase deficiency (LPLD)." (PMID 33594520, 2021). "This study used a mouse model to demonstrate that recombinant adipocytes modified to express LPL can alleviate lipoprotein lipase deficiency." (PMID 28969646, 2017). "Lipoprotein lipase deficiency (LPLD) is an autosomal recessive inherited disorder caused by loss-of-function mutations in genes involved in the lipoprotein lipase pathway." (PMID 28927429, 2017). "Genomic DNA analysis identified lipoprotein lipase deficiency due to compound heterozygosity including a novel p.Q240H mutation in exon 5 of the lipoprotein lipase (LPL) gene." (PMID 26337181, 2015). "Especially, LPL gene deficiency is the cause of type I hyperlipoproteinemia (familial hyperchylomicronemia)." (PMID 22028972, 2012). "Having shown that these lipoproteins are internalized and degraded by ECs, we next tested whether LpL deficiency and its resultant hyperchylomicronemia lead to aortic inflammation." (PMID 39649171, 2024). "Familial hyperchylomicronemia may be produced (among others) by mutations in the protein ApoAV, which is involved in the activation of LPL (Section 4) and increasing TG lipolysis." (PMID 38303975, 2023). "It was reported that the p.Thr143Met mutation, which could increase the activity of LPL, was identified in a patient with Familial hyperchylomicronemia." (PMID 35368694, 2022). "Thus, targeted delivery of human lipoprotein lipase into striated muscle tissue identifies a potential therapeutic target for lipoprotein lipase deficiency." (PMID 29304082, 2018). "Mutations in LPL cause LPL protein deficiency resulting in type 1 hyperlipoproteinemia." (PMID 28122634, 2017). "Familial LPL deficiency is a rare autosomal recessive disorder which is characterized by primary hyperchylomicronemia due to homozygous or compound heterozygous mutations of LPL gene as well as to homozygous mutations of APOC2,GPIHBP1, APOA5 or LMF1 genes." (PMID 24788417, 2014). "In addition, the known LPL gene mutation A98T has been described previously with lipoprotein lipase deficiency in the clinic." (PMID 24646025, 2014). "LPL activity is the shared result of all these genetic alterations that determine a consistent hyperchylomicronemia, known in the literature as type I hyperlipidemia." (PMID 36979789, 2023). "Its absence leads to hyperchylomicronemia after fasting or postprandial dosing because the LPL is responsible of the mediation of lipolysis of plasma chylomicron's triglyceride." (PMID 35242310, 2022).